TLR9 (toll like receptor 9)
Diseases named in the same sentence as TLR9 in open-access papers (continued):
Sharing a sentence is not in itself a finding about the gene and the disease.
lung carcinoma (continued). "Our recent evidence showed that Toll like receptor 9 (TLR9) signaling could enhance the growth and metastatic potential of human lung cancer cells through repressing microRNA-7 (miR-7) expression." (PMID 24004462, 2013). "PIK3R3 expressions have been associated with cancers like glioblastoma and ovarian cancer in prior studies, and recent studies have identified PIK3R3/AKT as the target of lung cancer molecule miR-7 which affects TLR9 signaling (TLR was discussed in a previous section)." (PMID 24369052, 2013). "Our previous study demonstrated that TLR9 signaling could enhance the tumor progression of human lung cancer cells in vitro and in vivo." (PMID 23133627, 2012). "Finally, we revealed that the expression of miR-574-5p was positively correlated with TLR9 and reversely correlated with Ches1 in lung cancer patients." (PMID 23133627, 2012). "Our previous study revealed that TLR9 signaling could contribute to the metastasis of human lung cancer." (PMID 23133627, 2012). "We previously demonstrated that TLR9 signaling could enhance the tumor progression of human lung cancer cells in vitro and in vivo." (PMID 23133627, 2012). "To elucidate the potential role of miR-574-5p in the effects of TLR9 signaling on the progression of human lung cancer cells, we validated our previous microarray platform and assessed the expression of miR-574-5p in 95D cells with or without CpG ODNs treatment by real time PCR analysis." (PMID 23133627, 2012). "However, the precise mechanisms for how TLR9 signaling was involved in tumor progression of human lung cancer were still far less clear." (PMID 23133627, 2012). "Furthermore, our work showing TLR9 agonist treatment can enhance survival in murine LAM could be translated into the clinic in future, particularly since TLR9 agonists have been approved for several cancers and are explored in clinical trials for lung cancer." (PMID 36798234, 2024). "Furthermore, activation of TLR9 signaling can inhibit the cleavage of the endogenous miR-7 precursor in lung cancer cells by inducing the expression of human antigen R (HuR), therefore reduce the level of mature miR-7 and accelerate the growth and metastatic progression of the cells." (PMID 26516313, 2015). "However, TLR9 response to CpG oligonucleotide (ODN) in human lung cancer cells could also enhance their growth and invasive potential in vitro and in vivo." (PMID 25788863, 2014). "However, whether HuR also contributed to the altered expression of miR-7 in TLR9 signaling stimulated human lung cancer cells remains to be elucidated." (PMID 24004462, 2013). "However, whether HuR was also involved in the expression of miR-7 in TLR9 signaling treated lung cancer cells still remains to be elucidated." (PMID 24004462, 2013). "Toll-like receptor (TLR) agonists can also re-activate immunity and the TLR9 agonist, CpG-ODN, has been effective in treating lung cancer in animal models." (PMID 36798234, 2024). "In contrast, clinical developments are underway utilizing TLR9 agonists, like CpG-A ODN and CpG-B ODN to activate pDCs and B cells, respectively, for the treatment of lung cancer." (PMID 36389785, 2022). "In our previous studies, we found that lung cancer epithelial cells were responsive to exogenous S1P, but the major source of TNF-α was related to the activation of TLR9." (PMID 36010601, 2022). "miR-574-5p also participates in the promotion of metastasis and invasion of lung cancer through PTPRU (protein tyrosine phosphatase, receptor type U) and TLR9 signaling." (PMID 32574204, 2020). "We incubated HEK-Blue cells expressing human TLR2, TLR3, TLR4, TLR5, TLR7, TLR8, TLR9, or the intracellular PRR protein NOD2 with 100 μg/ml DRibbles derived from the mycoplasma free lung cancer cell line UbiLT3." (PMID 27490927, 2016). "Besides, TLR9 signaling could increase the release of VEGF in a mouse model of lung cancer." (PMID 25788863, 2014).
lung carcinoma (continued). "And TLR9 signaling could alter biological character of lung cancer cells including promoting the proliferation and enhancing the metastatic potential of tumor cells, indicating that activation of TLRs signaling in lung cancer cells could contribute to the progression of lung cancer." (PMID 24004462, 2013). "Tlr9 activates inflammatory factors such as il-1 and il-8, increasing immune inhibitory factor il-10 secretion and MMP-2 expression to enhance the invasion and metastasis of lung cancer cells." (PMID 36991462, 2023). "The positive correlation between TLR9 expression and the TMB in lung cancer suggested that pDCs may act as a surrogate marker for a high TMB in lung cancer." (PMID 37435086, 2023). "For example, in murine models of lung cancer, direct inhalation of immunostimulatory CpG-ODN motifs, which activate Toll-like Receptor 9 (TLR9) signaling, stimulated anti-cancer activity by modifying the tumor microenvironment in favour of increased recruitment and activation of T cells." (PMID 35655772, 2022). "In particular, TLR9 activation in lung cancer epithelial cells increased the release of TNF-α, but not of IL-6, through an imbalance of the ceramide/S1P rheostat in favor of S1P." (PMID 36010601, 2022). "Here, instead, we found that S1P activity was related to S1PR3 on circulating cells of lung cancer patients but not by TLR9 (data not shown)." (PMID 36010601, 2022). "In a study in lung cancers, including the carcinoid cell line NCI-H727 showed miR-7 to directly target PI3KR3, the regulatory subunit of PI3K, and to reduce the metastatic potential by reducing the effect of TLR9 signaling." (PMID 29973528, 2018). "Lastly, two clinical trials using TLR9 agonists (IMO-2055, phase II; MGN1703, phase I) have been utilized as immunomodulators for lung cancer and found possible anti-tumor efficacy, either in combination with erlotinib (EGFR inhibitor) and bevacizumab (VEGFA inhibitor) or alone (MGN1703)." (PMID 29190881, 2017). "TLR9 signaling may alter the biological character of lung cancer cells, including promoting proliferation and enhancing the metastatic potential of tumor cells, indicating that the activation of TLR signaling in lung cancer cells may contribute to the progression of lung cancer." (PMID 24748977, 2014). "Besides, the important role of miR-574-5p in TLR9 signaling did not exclude other miRNAs that might be involved in TLR9 signaling in human lung cancer." (PMID 23133627, 2012).
COVID-19 (47 papers, 2020 to 2025). A disease caused by infection with severe acute respiratory syndrome coronavirus 2. "Other researchers have reported a significant correlation between the mutation (CC) genotype or the presence of the TLR9 rs5743836 C allele and the increased susceptibility and severity of coronavirus disease 2019 (COVID-19) infection." (PMID 40821978, 2025). "It has been hypothesized that for COVID-19, TLR9 activation is a subtle but potent factor causing hyperinflammation and thrombotic complications in vulnerable patients." (PMID 35847031, 2022). "TLR9 inhibition could thus be a strategy for treatment of the COVID-19 patients that are at risk for developing severe symptomatic infection." (PMID 36303774, 2021). "TLR9 inhibition could thus be a strategy worth considering for treatment of the specific COVID-19 patients that are at risk for developing severe symptomatic infection and further complicated clinical course due to underlying TLR9 skewing vulnerabilities." (PMID 33519463, 2020). "The novel hypothesis that TLR9 could be associated with COVID-19 pathology in vulnerable patients, positions TLR9 as a multifaceted drug target worth considering for preventing and/or treatment of critical conditions of SARS-CoV-2 infected patients." (PMID 33519463, 2020). "In this context, the following TLRs have been associated with the severity of COVID-19: TLR2, TLR3, TLR4, TLR7, TLR8 and TLR9." (PMID 41011507, 2025). "In NK cells, we identified COVID-19 severity-associated genes relating to the TLR4 and TLR9 signaling pathways and to the oncostatin M pathway." (PMID 40532694, 2025). "Given that mature neutrophils express all TLRs except TLR3, we analyzed the expressions of TLR7, TLR8 and TLR9 in normal human neutrophils after being treated with EVs from COVID-19 patients (n = 6) and HC subjects (n = 6), respectively." (PMID 37904132, 2023). "With the activation of TLR-7 and TLR-9 in COVID-19 mRNA vaccines, there are more alterations with pro-inflammatory cytokines such as interleukin 1 (IL-1) and interleukin 6 (IL-6)." (PMID 37091488, 2023). "In this study, we sought to deliver RBD antigen using a nanoparticle delivery system with CpG55.2 oligonucleotide adjuvant (TLR-9 agonist) to achieve a novel needle-free, mucosally delivered, COVID-19 vaccine." (PMID 37495639, 2023). "In summary, the unmethylated CpG motif CpG 684, the PAMP of toll-like receptor-9, in this study was shown to improve the humoral and cellular immune response of inactivated COVID-19 vaccine." (PMID 38051998, 2023). "The durability and breadth of our candidate vaccine remain to be determined, but it has been shown previously that nanoparticle-conjugated TLR9 agonists improve the potency, durability, and breadth of COVID-19 vaccines." (PMID 38006064, 2023). "There was a significant upregulation of mRNA of TLR3 (fold change = 2.9, P = 0.011), TLR7 (fold change = 2.2, P = 0.020), TLR8 (fold change = 2.9, P = 0.040), and TLR9 (fold change = 2.5, P = 0.001) in COVID-19-Group A in comparison to the Control-Group II." (PMID 35538443, 2022). "The mRNA expression of TLR3 (fold change = 3.4, P = 0.032), TLR7 (fold change = 2.0, P = 0.041), TLR8 (fold change = 2.8, P = 0.019), and TLR9 (fold change = 2.1, P = 0.016) was significantly upregulated in COVID-19- Group A compared with the Control-Group I." (PMID 35538443, 2022). "According to this, patients with COVID-19 presented lower TLR-9–mediated IFN-α production than healthy donors." (PMID 35943812, 2022). "Together, these data suggest an association of MyD88 and a panel of TLRs (i.e., TLR1, TLR2, TLR4, TLR5, TLR8, and TLR9) with disease progression in patients with COVID-19." (PMID 35682644, 2022). "In conclusion, our investigation indicated that the mRNA expressions of TLR3, TLR7, TLR8, and TLR9 are upregulated in the nasopharyngeal epithelial cells from COVID-19 patients." (PMID 35538443, 2022).
COVID-19 (continued). "It was seen that the transcript levels of TLR3, TLR7, TLR8, and TLR9 were overexpressed in the COVID-19 patients with clinical symptoms needing hospitalization as well as in those with clinical symptoms without needing for hospitalization compared to controls." (PMID 35538443, 2022). "There was a significant upregulation of mRNA of TLR3 (fold change = 2.1, P = 0.022), TLR7 (fold change = 1.9, P = 0.025), TLR8 (fold change = 2.0, P = 0.039), and TLR9 (fold change = 2.9, P = 0.024) in COVID-19-Group B compared with the Control-Group I." (PMID 35538443, 2022). "The serum of COVID-19 patients present high levels of mitonchondrial DNA (mtDNA), which contributes to the secretion of proinflammatory mediators via TLR9 activation." (PMID 35956081, 2022). "A significant positive correlation was observed between CRP and mRNA expression of TLR3 (rho = 0.85, P = 0.001), TLR7 (rho = 0.80, P = 0.004), TLR8 (rho = 0.78, P = 0.010), and TLR9 (rho = 0.48, P = 0.035) in the all COVID-19 cases." (PMID 35538443, 2022). "There was a significant upregulation of mRNA of TLR3 (fold change = 2.4, P = 0.017), TLR7 (fold change = 2.0, P = 0.009), TLR8 (fold change = 2.2, P = 0.004), and TLR9 (fold change = 2.9, P = 0.010) in COVID-19-Group B compared with the Control-Group III." (PMID 35538443, 2022). "In fact, it has recently been proposed that TLR9 plays a role in the development of severe COVID-19 manifestations and that TLR9 be targeted therapeutically." (PMID 35399111, 2022). "Gene analysis also revealed elevated expression of TLR7 and TLR9, leading to exaggerated immune response, in certain ethnic groups with higher COVID-19 mortality." (PMID 35956081, 2022). "Several studies have suggested the role of TLRs in enhancing humoral responses during COVID-19 infection, but so far, no study has examined the expression of TLR3, TLR7, TLR8 and TLR9 on respiratory epithelial cells from COVID-19 patients." (PMID 35538443, 2022). "Parallel to the expression of MyD88, the expression of TLR1, TLR2, TLR4, TLR5, TLR8 and TLR9 was significantly elevated in patients with severe and critical COVID-19." (PMID 35682644, 2022). "The increased circulating free DNA (cfDNA) in COVID-19 patients generated excessive mitochondrial ROS (mtROS) in cells in a dose-dependent manner, which was inhibited by a TLR9-specific antagonist." (PMID 35956081, 2022). "There was positive significant correlation between ESR and mRNA expression of TLR3 (rho = 0.71, P = 0.005), TLR7 (rho = 0.62, P = 0.011), TLR8 (rho = 0.65, P = 0.029), and TLR9 (rho = 0.40, P = 0.044) in all COVID-19 cases." (PMID 35538443, 2022). "We found that COVID-19 plasma exosomes significantly induced the expression of TLR3 and TLR9 in all subsets of immune cells tested, while COVID-19 plasma exosomes were unable to induce TLR7 expression in CD8+ T cells." (PMID 36526691, 2022). "More specifically, TLR3, TLR7, TLR8, and TLR9 were upregulated in the COVID-19 cases with clinical symptoms and needing hospitalization as well as in those with clinical symptoms but without requirement for hospitalization for supportive cares." (PMID 35538443, 2022). "There was positive significant correlation between Neutrophil–lymphocyte ratio and mRNA expression of TLR3 (rho = 0.62, P = 0.012), TLR7 (rho = 0.60, P = 0.013), TLR8 (rho = 0.49, P = 0.011), and TLR9 (rho = 0.39, P = 0.036) in all COVID-19 cases." (PMID 35538443, 2022). "The expression levels of TLR9 and levels of endogenous triggers for TLR9 activation are also influenced by diet which has been proposed to contribute to a severe outcome of COVID-19 in vulnerable patients." (PMID 34291074, 2021). "These antibodies activate platelets in the presence of TLR9 stimuli, stimuli that are prominent in COVID-19." (PMID 34013243, 2021). "Specifically, as regards the role of TLR9 in resistance against SARS-CoV-2 it has been proposed that there is an excessive TLR9 activation in severe COVID-19 pathology." (PMID 34753980, 2021).
COVID-19 (continued). "Another appropriate approach is to analyze variations in TLR9 expression levels in relevant patient samples such as sputum and/or lung lavage samples from patients with COVID-19 and in affected tissue biopsies from patients that died from severe COVID-19." (PMID 33519463, 2020). "TLR9 has also emerged as a promising therapeutic target for preventing and treating COVID-19." (PMID 41011507, 2025). "Although these data are limited, in aggregate they suggest that the various forms of AM all share the characteristic of activating both virus-associated (TLR3, TLR7, TLR8 or TLR9) and bacteria-associated (TLR2 and TLR4) innate receptors with severe COVID-19, KD and MIS-C." (PMID 36769320, 2023). "The authors report that the AstraZeneca COVID-19 vaccine stimulates innate immune responses by involving multiple pattern recognition receptors, particularly Toll-like receptor 9; this could explain the correlation along with the timing of lesion appearance." (PMID 37515110, 2023). "Modulation of TLR3, TLR7, TLR8, TLR9 in the epithelial cells of COVID-19 cases may estimate the disease severity and requirement for hospitalization." (PMID 35538443, 2022). "TLR9 launches inflammatory responses that culminate in endothelial-cell dysfunction, which may contribute to the severity of COVID-19 symptoms." (PMID 35847031, 2022). "It was seen that mRNA expression of TLR3 (fold change = 2.2, P = 0.004), TLR7 (fold change = 2.5, P = 0.038), TLR8 (fold change = 3.1, P = 0.018), and TLR9 (fold change = 3.0, P = 0.026) was significantly upregulated in the COVID-19- Group A in comparison to Control-Group III." (PMID 35538443, 2022). "It was observed that mRNA expression of TLR3 (fold change = 2.3, P = 0.016), TLR7 (fold change = 2.1, P = 0.033), TLR8 (fold change = 2.3, P = 0.022), and TLR9 (fold change = 2.4, P = 0.019) was significantly upregulated in the COVID-19- Group B versus Control-Group II." (PMID 35538443, 2022). "There was a significant positive correlation between percentage of oxygen saturation and transcript levels of TLR3 (rho = 0.37, P = 0.041), TLR7 (rho = 0.30, P = 0.026), TLR8 (rho = 0.35, P = 0.022), and TLR9 (rho = 0.39, P = 0.028) in the overall COVID-19 cases." (PMID 35538443, 2022). "Therefore, the analysis of the genotypes of TLR2, TLR3, TLR4, TLR6, TLR7, TLR8, and TLR9 is important for the study of COVID-19." (PMID 35327350, 2022). "It was observed that oxygen saturation, WBC count, Neutrophil–lymphocyte ratio, LDH level, CRP level, and ESR level had a significant positive correlation with the transcript levels of TLR3, TLR7, TLR8, and TLR9 in the COVID-19 Group A as well as COVID-19 Group B patients." (PMID 35538443, 2022). "In addition, a significant positive correlation was detected between WBC count and transcript levels of TLR3 (rho = 0.55, P = 0.020), TLR7 (rho = 0.59, P = 0.029), TLR8 (rho = 0.44, P = 0.012), and TLR9 (rho = 0.41, P = 0.034) in the whole COVID-19 cases." (PMID 35538443, 2022). "Activation of TLR9 results in MyD88-dependent inflammatory signalling, which may be of some relevance in COVID-19 when host-derived DNA is released due to tissue damage or if there are opportunistic bacterial infections." (PMID 33505220, 2021). "This TLR9-COVID-19 hypothesis, presented by Bezemer and Garssen, proposes that CpG islands in SARS-CoV-2 or mtDNA released from damaged host cells could trigger TLR9 activation and subsequently elicit pathogenic hyperinflammatory responses." (PMID 34834939, 2021). "In the context of COVID-19, this TLR9 axis of inflamm-aging could have consequence, just because older age is associated with high risk of developing severe complications of COVID-19." (PMID 34753980, 2021). "COVID-19 cfDNA induces mtROS production, which is attenuated by TLR9 inhibition." (PMID 33651717, 2021). "Next, we tested whether a TLR9-specific antagonist could inhibit overproduction of mtROS induced by COVID-19 plasma or purified cfDNA (positive control)." (PMID 33651717, 2021).